TF (transferrin)
Diseases named in the same sentence as TF in open-access papers (continued):
Sharing a sentence is not in itself a finding about the gene and the disease.
iron overload (continued). "The results of the Cox analyses remained materially unchanged when excluding patients with iron overload (i.e., transferrin saturation >45%; N=33), when excluding patients using iron supplementation (N=41) and when excluding patients with suspected UTI (N=66)." (PMID 40569672, 2025). "This is characterized by iron overload, mainly in reticulo-endothelial macrophages, and low transferrin saturation." (PMID 39940646, 2025). "Meanwhile, the TF saturation was significantly higher in the young (92.99 ± 1.68% vs. 26.70 ± 8.18%, p < 0.001) and old iron overload groups (94.13 ± 0.98% vs. 20.58 ± 3.89%, p < 0.001) compared with their respective control groups." (PMID 40871609, 2025). "Iron overload—as evidenced by elevated ferritin and transferrin saturation —can be from increased iron absorption or turnover from ineffective erythropoiesis." (PMID 40905013, 2025). "Iron overload in aging and transfusional individuals is characterized by high ferritin, augmented non-transferrin-bound iron, and oxidative DNA damage, which all raise the risk of cancer, especially hepatocellular carcinoma." (PMID 40656262, 2025). "In pregnant populations, previous studies have reported iron overload in individuals with hypertensive disorders of pregnancy, characterized by elevated serum iron, ferritin, and transferrin saturation levels." (PMID 41280380, 2025). "Typically, transferrin-bound iron predominates, but non-transferrin-bound iron (NTBI) can emerge in plasma during iron overload." (PMID 40066336, 2025). "Sustained resolution of iron overload, indicated by reduced transferrin saturation, was achieved within 52 weeks of pegcetacoplan treatment in 16 of these 22 patients (72.7%); iron overload had not resolved in 6 patients (27.3%) (p < 0.05)." (PMID 41155315, 2025). "Of the 80 patients randomized in PEGASUS, baseline iron overload (i.e., serum transferrin saturation ≥ 50%) was present in 27 patients (33.8%)." (PMID 41155315, 2025). "Of 80 patients randomized in PEGASUS, 27 (33.8%) had baseline iron overload (serum transferrin saturation ≥ 50%)." (PMID 41155315, 2025). "Transfusion-related iron overload: for the study, iron overload refers to a serum ferritin level of 200-300 μg/L or more and transferrin saturation of 45% or more." (PMID 40687162, 2025). "High ferritin levels indicate iron overload and saturation of transferrin, allowing non-transferrin bound iron to accumulate and catalyse reactive oxygen species generation." (PMID 38649459, 2024). "In cases of iron overload, the excess circulating iron can exceed the binding capacity of transferrin, leading to the formation of non-transferrin-bound iron." (PMID 39769044, 2024). "Here, we present a case where a 34-year-old with a history of severe alcohol use disorder presented with high iron, ferritin and transferrin saturation levels indicative of iron overload." (PMID 38361672, 2024). "Those with iron overload will generally have raised serum ferritin (SF) and transferrin saturation (SF)." (PMID 39202328, 2024). "Participants were divided into two groups based on transferrin saturation (≥50% as a reference for iron overload)." (PMID 39262540, 2024). "This aligns with our observations of a beneficial range for transferrin saturation and the detrimental effects of iron overload indicated by high plasma ferritin levels." (PMID 39796572, 2024). "In the case of iron overload, when iron is overloaded, transferrin is saturated, excess iron forms non-transferrin-bound iron (NTBI) in the circulation." (PMID 39600338, 2024). "A high proportion (57%) of iron overload (transferrin saturation >45%) among women with obesity-T2D is notable." (PMID 40895225, 2024). "Later, the definition of dysmetabolic iron overload (DIOS) was refined as HF with normal or mildly increased transferrin saturation, metabolic abnormalities and a specific amount of hepatic iron excess with liver biopsy or MR imaging." (PMID 38255312, 2024).
iron overload (continued). "The complex of the two can bind to transferrin and reduce transferrin and transferrin receptors affinity to prevent the occurrence of iron overload." (PMID 37061523, 2023). "In iron-overload conditions, transferrin saturation is high, and consequently, serum iron is high or TIBC values are low." (PMID 36902180, 2023). "Screening using both serum ferritin and transferrin saturation will identify the majority of individuals who will go on to develop iron overload." (PMID 37067673, 2023). "Iron overload and increased non-transferrin-bound iron lead to ROS production and subsequent oxidative damage." (PMID 37628834, 2023). "All patients present increased transferrin saturation and high serum ferritin levels, and hepcidin is abnormally low relative to iron overload." (PMID 36986429, 2023). "The few patients described in the literature present high levels of serum iron, very low levels of transferrin, high levels of serum ferritin, and signs of iron overload." (PMID 36986429, 2023). "Iron overload is defined by high serum ferritin (above 300 ng/L) and high transferrin saturation (Tfsat > 40%)." (PMID 36986429, 2023). "Systemic forms of iron overload are characterized by increased serum ferritin and high transferrin saturation." (PMID 36986429, 2023). "Chelators used to treat iron overload in vivo have a high affinity for iron that is lower than transferrin, but allows to scavenge all non-transferrin-bound iron (NTBI) to prevent oxidative damage." (PMID 37117329, 2023). "The increase in systemic iron levels leads to tissue iron overload, increased serum ferritin and transferrin saturation, and, eventually, the appearance of NTBI." (PMID 36986429, 2023). "Serum transferrin saturation (TSat) is a useful marker especially in assessing iron overload but its calculation is dependent upon measurement of serum iron and transferrin levels; hence is influenced by factors affecting these two analytes." (PMID 36240192, 2022). "The elevated transferrin saturation and serum iron levels observed in iron overload lead to the formation of a non-transferrin-bound iron (NTBI) fraction with high pro-oxidant activity." (PMID 36428877, 2022). "It has been shown that TSAT is a more sensitive indicator for diagnosing iron overload; When the TSAT exceeds 80–85%, non-transferrin-bound iron appears in the serum and can cause organ damage due to its high toxicity." (PMID 36178540, 2022). "Characterized by high serum ferritin with low transferrin saturation, aceruloplasminemia uniquely combines brain, liver and systemic iron overload." (PMID 35585918, 2022). "Within our cohort of patients with CDA II enrolled in our Registry of hereditary anemias, we selected 28 cases showing iron overload, defined as transferrin saturation (TSAT) > 45%." (PMID 35163229, 2022). "In patients with epilepsy, transferrin saturations are increased as a surrogate marker for iron overload and the presence of altered iron suggests dysfunctional regeneration after seizure." (PMID 34817680, 2022). "Most patients have evidence of iron overload, as indicated by increased serum iron, transferrin saturation, and serum ferritin." (PMID 36140729, 2022). "Iron overload is typically detected by measuring serum transferrin saturation (the amount of ferric iron bound to the carrier protein transferrin in the circulation; >45 percent indicates iron excess) in conjunction with serum ferritin concentration." (PMID 36034918, 2022). "We herein described a case series of 28 CDA II patients showing iron overload with high transferrin saturation and very low levels of hepcidin." (PMID 35163229, 2022). "The similar degree of iron overload severity in both the heart and pancreas prove that the pancreas, like the heart, exclusively loads non-transferrin-bound iron (NTBI)." (PMID 37492672, 2022). "This can lead to iron overload and the formation of the non-transferrin-bound iron (NTBI) fraction, which, like LPI, has high pro-oxidant activity." (PMID 36428877, 2022).
iron overload (continued). "Usually, the presence of hyperferritinemia with a transferrin saturation rate >60% suggests hereditary hemochromatosis, whereas a value of 45–60% suggests other possible diseases consistent with iron overload." (PMID 35741435, 2022). "Iron disorders, in particular iron overload, which is characterized by elevated transferrin saturation and baseline plasma iron concentration, are associated with increasing NTBI fractions." (PMID 36428877, 2022). "Conversely, if transferrin in plasma decreases, iron binds to albumin and anions to form non-transferrin-bound iron (NTBI), which can be absorbed by tissue cells, causing iron overload." (PMID 35127725, 2021). "NTBI appears in circulation in diseases of iron overload when the iron-binding capacity of transferrin is exceeded." (PMID 34480898, 2021). "Initially, transferrin saturation increases, which is the earliest biochemical marker of iron overload." (PMID 34987900, 2021). "The extent to which serum ferritin criteria identified subjects with iron overload varied compare with the transferrin saturation criteria." (PMID 34795732, 2021). "Here we present a case where a simple heterozygote in combination with alcoholism developed high ferritin and high transferrin saturation levels indicative of iron overload." (PMID 33596964, 2021). "Using transferrin saturation greater than forty-five percent criterion, six subjects was identified as having iron overload and they were different from the subjects using the serum ferritin greater than 300ng/ml criterion." (PMID 34795732, 2021). "Serum transferrin saturation more than 55% and ferritin levels greater than 200 in pre-menopausal women and 300 in men and post-menopausal women is called iron overload." (PMID 34987900, 2021). "The adopted definition of iron overload included a second criterion – transferrin saturation greater than forty-five percent." (PMID 34795732, 2021). "The URennes, manual T2*, and T2* mapping protocols had similar power to detect patients with elevated ferritin or transferrin saturation and clinically suspected hepatic iron overload." (PMID 32587421, 2020). "In the present study, the frequency of P47S in African Americans from the HEIRS Study with high saturated transferrin and/or high serum ferritin (signs of iron overload) was 2.2% (OR 1.68, CI 1.07–2.65, p < 0.023)." (PMID 31980600, 2020). "Iron overload has been also described in HSt, particularly in the DHSt form and Gardos chanellopathy, where hyperferritinemia, high transferrin saturation or clinical iron overload are very frequent." (PMID 32655575, 2020). "In systemic iron overload, excess iron cannot be matched by sufficient unsaturated iron binding capacity and results in the formation of non-transferrin bound iron (NTBI)." (PMID 32711469, 2020). "KO mice on a standard diet (380 ppm Fe) have normal serum iron, total iron-binding capacity (TIBC) and transferrin saturation but significantly elevated serum ferritin, an indicator of tissue iron-overload." (PMID 31571584, 2019). "Transferrin saturation is a composite measure of serum iron and total iron binding capacity, and is a strong predictor of iron overload in clinical practice." (PMID 30717475, 2019). "In a small study of non-transfusion dependent thalassemia patients, PAH was relatively common (10%) and was associated with previous multiple transfusions, splenectomy and non-transferrin bound iron (a marker of iron overload)." (PMID 29904352, 2018). "This however will differ in cases of iron overload, where saturation of transferrin occurs resulting in an increase in free, circulating ferric plasma iron, not bound to transferrin." (PMID 30510932, 2018). "The first reported patient was a 7-years old girl with traces of plasma transferrin and systemic iron overload that led to early death due to congestive heart failure." (PMID 30420953, 2018).
iron overload (continued). "In contrast, others have found a doubling of the OR for developing T1D in those with a transferrin saturation above 50% (a measure of iron overload)." (PMID 29113123, 2017). "We used the Tfr2 KI animals (α+β0), in which circulating iron levels are normal, and the Tfr2 KO mice (α0β0), that have severe iron overload in addition to increased serum ferritin and transferrin saturation." (PMID 28540293, 2017). "It was reported that ferritin, in combination with transferrin saturation, has superior prognostic value in determining iron overload when compared to ferritin alone." (PMID 27956374, 2017). "First, iron overload led to a significant increase in serum iron (Fe (III) bound to serum transferrin) and in the hematologic indices HtC, MCV, MCH, RDW, Pt, and MPV, without significant changes in RBC and WBC counts, serum Hb values, and MCHC." (PMID 27574973, 2016). "None of the 18 participants had any other biochemical evidence of iron overload, such as high transferrin saturation." (PMID 27007895, 2016). "One of the first biochemical parameters that appear changed in patients with iron overload is transferrin saturation." (PMID 26197432, 2015). "The biochemical penetrance (i.e., presence of iron overload by transferrin saturation and serum ferritin concentration only) was similar to estimates from previous studies of large prospective cohorts." (PMID 26365338, 2015). "We found that both 4- and 8-week HFe-fed rats had iron overload as indicated by increased plasma non-transferrin bound iron (NTBI)." (PMID 24400127, 2014). "In the present study, chronic HFe consumption induced iron-overload condition as indicated by an increased plasma non-transferrin bound iron (NTBI)." (PMID 24400127, 2014). "Despite a similar level of hyperferritinaemia, the C282Y/H63D patients who came to medical attention had a milder plasma iron overload, reflected by a lower transferrin saturation median (52.0% vs. 84.0%; p<0.0001)." (PMID 24339903, 2013). "We found significantly decreased hepcidin concentration, combined with increased transferrin saturation (greater than 50%) and high level of serum ferritin (greater than 500 ng/mL) in cirrhotic patients, which indicated body iron overload." (PMID 23776499, 2013). "Iron overload is best monitored by periodic determinations of serum ferritin levels and transferrin saturation in frequently transfused patients in the steady state." (PMID 22924029, 2012). "Serum ferritin levels >1000 μg/L and transferrin saturation >50% in the steady state are suggestive of iron overload." (PMID 22924029, 2012). "Iron was used at the concentrations comparable with the plasma levels of non-transferrin-bound Fe3+ in CAPD patients (10 mM) or in iron overload patients (50–100 mM)." (PMID 22203913, 2011). "Biochemical markers of iron overload (namely serum ferritin and transferrin saturation), as well as CRP levels, were significantly higher in MDS patients as compared to controls." (PMID 21886780, 2011). "Classical ferroportin disease is characterized by hyperferritinemia, normal transferrin saturation, and iron overload in macrophages." (PMID 20691492, 2010). "Hyperferritinemia, a normal to low transferrin saturation and Kupffer cell iron storage, presenting as hepatic and spleen iron overload, are considered characteristic features of classical ferroportin disease." (PMID 20691492, 2010). "In another case, monthly plasma infusions provided sufficient transferrin to maintain a hemoglobin of 12 g/dL and enabled phlebotomy as simultaneous therapy for iron overload." (PMID 20631898, 2010). "Increased transferrin saturation and hepatocellular iron overload, in addition to hyperferritinemia and macrophage iron loading, is considered characteristic for the non-classical phenotype." (PMID 20691492, 2010). "Exclusion criteria will include iron overload (transferrin saturation >50% or ferritin >800 μg/l), or previous intolerance of either oral or intravenous iron supplements." (PMID 19500381, 2009).
iron overload (continued). "Other blood markers, such as transferrin saturation and soluble transferrin receptor, have proven to be even less successful in establishing the diagnosis of iron overload." (PMID 19852846, 2009). "In that study, very high levels of serum ferritin and transferrin saturation greater than 100% were used as surrogates for iron overload." (PMID 19852846, 2009). "Iron overload is marked by increases in both transferrin-bound and free, non-transferrin-bound iron (NTBI) in blood." (PMID 18254965, 2008). "The individual is at risk of developing iron overload/HH and it is recommended that the indices of iron overload (fasting, serum transferrin saturation and ferritin) be regularly monitored." (PMID 17134494, 2006). "Although all these patients had iron overload, the individuals homozygous for C282Y had significantly higher transferrin saturation and ferritin levels (77.5% and 2264.80 ng/ml, respectively) than did those with other mutations (p < 0.001)." (PMID 16878186, 2006). "Symptomatic individuals have biochemical evidence of iron overload (elevated serum transferrin saturation and ferritin concentration) and such biochemical evidence is found even in the absence of symptoms." (PMID 17134494, 2006). "Furthermore, the administration of iron-free (apo) transferrin has been shown to reduce iron overload symptoms in β-thalassemic mice, likely by binding NTBI." (PMID 40650208, 2025). "It has been proposed that decreased transferrin reabsorption during iron overload may serve as a protective mechanism to attenuate tubular iron burden." (PMID 41316290, 2025). "This is characterized by liver hepatocytes iron overload and high transferrin saturation." (PMID 39940646, 2025). "Elevated transferrin saturation may occur in conditions like iron overload or hemochromatosis but is rare in pregnancy." (PMID 40486642, 2025). "Following the establishment of the iron overload model, the analysis of the iron test results revealed significantly increased serum iron levels, TIBC, and TF saturation in the iron overload groups compared with the control groups, indicating a higher iron concentration in the bloodstream." (PMID 40871609, 2025). "Transferrin levels are regulated by hepcidin, a peptide secreted by hepatocytes, so the liver is typically the first organ to exhibit signs of iron overload when iron overload occurs in the body." (PMID 39206119, 2024). "Elevated serum ferritin (1443 ng/mL) and transferrin saturation (84%) suggested iron overload." (PMID 39171001, 2024). "It was found that the presence of the H63D mutation was associated with a significant increase in serum transferrin saturation but did not cause significant iron overload in both homozygotes and heterozygotes." (PMID 39867034, 2024). "Interestingly, biliary iron excretion and enterohepatic recycling of non-transferrin-bound iron have been described in models of iron overload or when transferrin is saturated." (PMID 37671923, 2023). "Iron overload leading to reduced serum transferrin saturation (TF) has also been studied." (PMID 37111212, 2023). "General population screening is not recommended but individuals of European descent with any clinical symptoms or signs compatible with the diagnosis or a family history of iron overload should be evaluated with genetic testing and measurement of serum transferrin saturation and ferritin levels." (PMID 37067673, 2023). "Accordingly, iron overload may be proven in patients with elevated ferritin, despite them having normal transferrin saturation." (PMID 34067164, 2021). "Therefore, this study aims to determine the correlations between iron overload (serum ferritin and transferrin saturation) and specific immune cells (CD4)." (PMID 34239727, 2021). "In contrast, transferrin saturation may be the better biomarker for tissue iron stores and may better detect iron overload." (PMID 34439443, 2021).